IL10 (interleukin 10)
Diseases named in the same sentence as IL10 in open-access papers (continued):
Sharing a sentence is not in itself a finding about the gene and the disease.
muscle atrophy (1 paper, 2023). The loss of muscle tissue due to inactivity or disease. "We showed that intramuscular IL-10 injections in transgenic SOD1G93A mice counteract skeletal muscle atrophy, directly stimulating SC differentiation and MΦ polarization." (PMID 37048088, 2023). "Also, IL-10 influenced the MΦ profile during chronic muscle atrophy." (PMID 37048088, 2023).
myelofibrosis (1 paper, 2025). A partial or complete replacement of the bone marrow stroma by fibrous tissue. "Selinexor has also been shown to reduce the plasma levels of many key pro-inflammatory cytokines (e.g., IL-6, TGFβ, IL-1β, IL-10, IFN-γ, TNF-α) in patients with myelofibrosis, and also in ex vivo studies with PBMCs." (PMID 40565816, 2025).
myoma (1 paper, 2021). "Our study results demonstrated significant reduction in the expression of inflammatory cytokines IL6 and IL10, influenced by UPA therapy, when a substantial decrease in myoma volume after treatment was observed." (PMID 34442017, 2021).
myotonic dystrophy (1 paper, 2022). An inherited progressive disorder affecting the muscles. "Further exploration of IL-10 regulatory mechanisms and the functional role of Treg-derived IL-10 in the pathogenesis of myotonic dystrophy is required." (PMID 35931697, 2022).
neonatal encephalopathy (1 paper, 2022). "Our findings support a potential role for IL-10 as a biomarker for adverse outcomes after neonatal encephalopathy." (PMID 33674741, 2022).
neonatal lupus (1 paper, 2023). "We suppose that the determination of serum IL-10 in combination with the determination of anti-SS-A/Ro antibody could be considered as a useful biomarker for assessing the risk of neonatal lupus." (PMID 37371554, 2023). "Perhaps the determination of serum IL-10 in conjunction with the determination of anti-SS-A/Ro antibodies could be a useful marker for assessing the risk of neonatal lupus." (PMID 37371554, 2023).
nephrocalcinosis (1 paper, 2026). Nephrocalcinosis is a disorder that occurs when too much calcium is deposited in the kidneys. "Serum levels of BUN and creatinine were indicative of Mφ‐IL10's ability to ameliorate the decline in renal function induced by nephrocalcinosis." (PMID 41573378, 2026). "In this study, we constructed a macrophage model for continuous IL‐10 secretion and found that macrophage transplantation had a significant therapeutic effect on glyoxylic acid‐induced nephrocalcinosis in mice." (PMID 41573378, 2026). "This study offers a practical strategy for the application of IL‐10 and macrophage transplantation in the treatment of nephrocalcinosis." (PMID 41573378, 2026). "Our data suggest that macrophage‐based delivery of IL‐10 to the kidney can be a potential treatment method for nephrocalcinosis." (PMID 41573378, 2026).
nervous system injuries (1 paper, 2013). "After central nervous system injuries, IL-10 was shown to improve neurological outcomes by reducing the number of apoptotic cells." (PMID 24278397, 2013).
neuralgia (1 paper, 2018). "In a recent study, on the effects of intrathecal injection of methylprednisolone on postherpetic neuralgia, CSF IL-8 increased 8–9 times while the cyto/chemokines IL-1, IL-10, and TNF-α were not affected over time, compared to controls." (PMID 30261896, 2018).
Neurodevelopmental delay (1 paper, 2020). "By contrast, in the absence of alcohol-exposure, activation of a network including IL-2, TNF-β, IL-10, and IL-15 was associated with neurodevelopmental delay." (PMID 31992316, 2020). "Network 1 included IL-2, TNF-β, IL-10, and IL-15 and was defined as the Alcohol-Independent Delay Network, as this network was activated specifically in controls with neurodevelopmental delay." (PMID 31992316, 2020). "For controls, we found higher average levels of a subset of cytokines including IL-4, IL-1β, PlGF, GM-CSF, SAA, IL-15, TNF-β, VEGF-D, IL-12p70, Tie-2, IL-2, IL-17α, IFN-ɣ, and IL-10 in children with neurodevelopmental delay (C/ND), compared to that of their typically developing (C/TD) counterparts." (PMID 31992316, 2020). "Control children experiencing neurodevelopmental delay (C/ND) showed activation of what we defined as the Alcohol-Independent Delay Network (network 1) that included IL-2, TNF-β, IL-10, and IL-15." (PMID 31992316, 2020). "Children with alcohol-independent neurodevelopmental delay (C/ND) showed activation of a single network, the Alcohol-Independent Neurodevelopmental Delay Network (network 1; IL-2, IL-15, TNF-β, and IL-10)." (PMID 31992316, 2020). "Based on our findings, we propose that elevations in IL-2, IL-15, TNF-β, and IL-10 may represent a non-specific immune profile broadly associated with neurodevelopmental delay during childhood, rather than serving as a more specific biomarker of any one neurodevelopmental disorder." (PMID 31992316, 2020).
neurological autoimmune diseases (1 paper, 2024). "For instance, previous clinical studies have demonstrated that IA stimulates the secretion of IL-10 by immune cells in patients with neurological autoimmune diseases, leading to a less pronounced decrease compared with other cytokines or even an increase in IL-10 plasma levels." (PMID 38473836, 2024).
neutrophil leukemia (1 paper, 2023). "RNA-seq analysis of the Treg subpopulation from the murine CLL model revealed its unique phenotype characterized by upregulation of multiple factors, including Il10, Ifnγ, and the chemokines Ccl3/4/5 Cxcl13, which likely contribute to the neutrophil leukemia-supporting phenotype." (PMID 37817276, 2023).
obstructive uropathy (1 paper, 2024). "IL-10 has a protective role in the adult model of obstructive uropathy." (PMID 38448513, 2024).
optic neuropathies (1 paper, 2022). "Experimental studies in various disease models addressed mechanisms of action and indicated modulation of neurotrophic factors (IGF-1, BDNF, CNTF, FGF-2, TNF-α) and immunomodulators (IL-10, IL-6, COX-2, NF-κB) by electrical stimulation of the eye in optic neuropathies." (PMID 35361287, 2022).
organophosphorus poisoning (1 paper, 2024). "Additionally, anti-inflammatory agents, such as interleukin-10 (IL-10), have showed promise in reducing the inflammatory response associated with organophosphorus poisoning." (PMID 38327393, 2024).
ovarian hyperstimulation syndrome (1 paper, 2025). A complication of ovulation induction in infertility treatment. "Furthermore, elevated IL-10 has been observed in pathological conditions such as ovarian hyperstimulation syndrome and in obese women, where it is associated with markers of lower oocyte quality." (PMID 41373524, 2025).
overnutrition (1 paper, 2022). An imbalanced nutritional status resulting from excessive intake of nutrients. "In fact, chronic overnutrition reduces activation of the Wnt/β-Catenin pathway in WAT cDC1s, a pathway that suppresses inflammation through enhanced IL‐10 production, which is an important regulatory mechanism involved in fat expansion." (PMID 34983945, 2022).
palmoplantar pustulosis (1 paper, 2016). A rare skin disease characterized by chronic eruption of sterile pustules on an erythematous and desquamative background, affecting the palms and soles, sometimes also the lateral aspects of hands and feet. "IL-10 and the IL-10 family of cytokines are involved in genetic susceptibility to psoriasis vulgaris and palmoplantar pustulosis." (PMID 27774448, 2016).
pancreatic NET (1 paper, 2020). "Our experiments in BON-1 cells derived from a pancreatic NET revealed significant treatment-related increase in TNFα synthesis paralleled by a significant reduction in IL-6 and IL-10 expression; this cytokine profile reflects the ability of lanreotide to induce a Th1 cytotoxic immune-response." (PMID 32766136, 2020).
panuveitis (1 paper, 2023). A disorder characterized by inflammation of the entire uvea which includes the iris, ciliary body, and choroid. "Additionally, there was a trend towards elevated levels of IL10+ T cells in aqueous humor from patients with FHU compared with those from acute uveitis and panuveitis patients." (PMID 36715869, 2023).
Pasteurella multocida infection (1 paper, 2023). "It was also found that P0910 and ΔOmpH in Pasteurella multocida infection activated the expression of ropE, HSPBP1, FERH, ATP10A, ABCA13, RRP7A, IL-10, IFN-γ, IL-17A, EGFR and dnaJ." (PMID 36977260, 2023).
periapical abscess (1 paper, 2021). "In the periapical abscess, cluster H metabolites are mostly known to be correlated to M2 polarization and IL-10 expression; for example, arsenous acid and cholesterol can induce anti-inflammatory M2 polarization." (PMID 34539639, 2021).
peritoneal carcinoma (1 paper, 2021). A peritoneum cancer that is located in the inside of the abdomen. "As an IL10 ELISA is far simpler and more convenient than detecting and quantitatively measuring free peritoneal cancer cells, so this may be a preferable method for assessing the risk of PR." (PMID 33911154, 2021).
pharyngeal carcinomas (1 paper, 2016). "IL-10 is not expressed in epithelial cells of normal tissues, but IHC analysis has demonstrated significantly stronger IL-10+ staining of epithelial cell cytoplasm in human oral and pharyngeal carcinomas compared with keratinocytes or inflammatory cells in normal epithelium." (PMID 28053372, 2016).
pharyngitis (1 paper, 2025). Inflammation of the throat most often caused by viral and bacterial infections. "In pharyngitis, KHJ reduced pathological damage, downregulated interleukin 1β (IL-1β), interleukin 6 (IL-6), prostaglandin E2 (PGE2), and elevated interleukin 10 (IL-10)." (PMID 41357871, 2025).
plasma cell tumors (1 paper, 2012). "The NF-κB2 mutant p80HT promotes the development of plasma cell tumors by transcriptional activation of genes critical for the generation, proliferation and survival of plasma cells, including cyclin D1, cyclin D2, Blimp1, survivin, IL-10 and IL-15." (PMID 22642622, 2012).
pleural tumors (1 paper, 2023). "MC38 cells were intrapleurally injected into IL-10−/− and WT mice; then, 10 days later, MPEs and pleural tumors were collected and analyzed." (PMID 37533789, 2023).
pneumoconiosis (1 paper, 2018). An occupational lung disorder caused by inhalation of dust particles. "However, a study of 72 coal workers with pneumoconiosis showed that lavage fluid IL-10 levels were significantly increased compared to controls, but serum IL-10 levels were not modulated." (PMID 30176916, 2018).
podoconiosis (1 paper, 2024). A disease of the lymphatic vessels of the lower extremities that is caused by chronic exposure to irritant soils. "The cytokine profile for podoconiosis patients by stage severity suggests trends of reduced IL-10 levels as the disease becomes more severe, while TNF-α appears to increase with severity." (PMID 39689160, 2024). "However, with inflammatory markers down, it makes sense that there are lower than normal IL-10 levels as it is typically seen as a potent anti-inflammatory and could explain certain differences in presentation between SLE and podoconiosis." (PMID 39689160, 2024).
POEMS syndrome (1 paper, 2015). POEMS syndrome is a paraneoplastic syndrome characterized by polyradiculoneuropathy (P), organomegaly (O), endocrinopathy (E), clonal plasma cell disorder (M), and skin changes (S). "Second, in POEMS syndrome there is overproduction of proinflammatory cytokines, including TNFα, IL1β, IL10, IL6, VEGF, similarly to what is observed in MCD and KICS, suggesting that these three clinical entities partially overlap." (PMID 25607954, 2015).
polyarticular JIA (1 paper, 2017). "Our study confirm and extend these findings as a significant positive association was evident between the IL-10 (-1082) AA genotype and susceptibility to polyarticular JIA among studied patients (OR: 4.3; P <0.01)." (PMID 28257625, 2017). "Moreover, we observed a significant positive association between the IL10 –1082 AA gene variant and susceptibility to polyarticular JIA." (PMID 28257625, 2017). "Of note, we observed that patients with polyarticular JIA did show significantly lower serum IL-10 levels compared to patients with systemic JIA and those with oligoarticular subtypes." (PMID 28257625, 2017).
pregnancy disorder (1 paper, 2024). A disorder that is related to pregnancy. "Previous animal studies have demonstrated that IL-10 improves pregnancy outcomes in mice with pregnancy disorders." (PMID 39171524, 2024).
Premature ovarian insufficiency (1 paper, 2021). Amenorrhea due to loss of ovarian function before the age of 40. "An imbalance between pro-inflammatory cytokines such as IFNγ and TNFα and anti-inflammatory cytokines such as IL-10 has also been reported to play a critical role in the pathological mechanism of premature ovarian insufficiency." (PMID 34868029, 2021).
Premature rupture of membranes (1 paper, 2019). Premature rupture of membranes (PROM) is a condition which occurs in pregnancy when the amniotic sac ruptures more than an hour before the onset of labor. "The impact of preterm premature rupture of membranes >12 h on IL-8/IL-10 ratios in cord blood was of borderline significance." (PMID 31001484, 2019).
proctocolitis (1 paper, 2020). Inflammation of the rectum and colon. "Another immunological feature of fecal samples from infants with proctocolitis was a reduced content of IL10." (PMID 32121004, 2020). "Thus, reduced fecal IL10 could explain bleeding related to gut inflammation in the Proctocolitis group." (PMID 32121004, 2020).
progeroid syndrome (1 paper, 2024). A group of rare genetic disorders which mimic physiological aging, making affected individuals appear to be older than they are. "Moreover, in Werner patients, another progeroid syndrome, a Th2-like secretory phenotype has been found with high serum levels of IL-4 and IL-10." (PMID 38474366, 2024).
promyelocytic leukaemia (1 paper, 2015). "It must be noted that the regulation of the expression and synthesis of BAFF by IL-10 and IFN-γ at the transcriptional level has also been demonstrated in human promyelocytic leukaemia cell cultures." (PMID 25085377, 2015).
proteinopathy (1 paper, 2021). "Taken together, it would seem that the outcomes of Il-10 signaling in mouse models that recapitulate PD-relevant proteinopathy as reported in our study are physiologically distinct from the acute toxin models of dopaminergic neurodegeneration." (PMID 33741985, 2021). "Together, these observations indicate that preconditioning the neuraxis with Il-10-related immunosuppressive signaling can lead to exacerbation of αSyn proteinopathy via altering neuronal autophagic pathways." (PMID 33741985, 2021). "Because of previously reported data that IL-10 can inhibit autophagy, we reasoned that this might explain mechanistically the effect of Il-10-mediated worsening of αSyn proteinopathy." (PMID 33741985, 2021).
pulmonary sarcoidosis (1 paper, 2020). Sarcoidosis affecting the lung parenchyma. "IL-10 is increased in active pulmonary sarcoidosis as a compensatory response to increased expression of proinflammatory cytokines." (PMID 33324666, 2020).
Pv (1 paper, 2020). "In the adjusted analysis, we observed a positive association of Pv infection with IFN-α and IL-12 peripheral plasma concentration and with IL-10 placental plasma concentration." (PMID 32365058, 2020).
radiculopathy (1 paper, 2019). Disease involving a spinal nerve root (see spinal nerve roots) which may result from compression related to intervertebral disk displacement; spinal cord injuries; spinal diseases; and other conditions. "Like IL-4, IL-10 has a short half-life, thus making gene therapy a desirable route of administration, particularly in patients requiring local IL-10 expression, such as in individuals with low back radiculopathy." (PMID 31921220, 2019).
radiodermatitis (1 paper, 2021). A cutaneous inflammatory reaction occurring as a result of exposure to biologically effective levels of ionizing radiation. "The endpoints were radiodermatitis scale, histological analysis HE, Picrius Sirius and the gene expression of interleukin-10 (IL-10) and matrix metalloproteinase-9 (MMP-9)." (PMID 33656099, 2021).
Reiter’s syndrome (1 paper, 2022). "CD8+ T-cell isolated from Reiter’s syndrome patients led to the identification of an autoreactive T cells specific toward an epitope encoded by human Interleukin-10 (IL-10)." (PMID 35222346, 2022). "Given the immunosuppressive role of IL-10, the deletion of IL-10 producing cells could have a profound impact on the pathology of Reiter’s syndrome." (PMID 35222346, 2022).
renal tubular acidosis (1 paper, 2023). A group of genetic disorders of the kidney tubules characterized by the accumulation of metabolically produced acids with elevated plasma chloride, hyperchloremic metabolic acidosis. "We consider that the activated T cells produce more IL-4, IL-10, IFN-γ and TNF-α during pSS complicated by renal tubular acidosis, leading to the activation of B cells and thus more autoantibodies." (PMID 37391717, 2023).
retinal artery occlusion (1 paper, 2007). An occlusion of the retinal artery. "The purpose of the present study was to investigate a hypothesized association between the haplotype-tagging IL10 -592C>A polymorphism and the presence of retinal artery occlusion (RAO)." (PMID 17438520, 2007). "Distribution of IL10 -592C>A genotypes in retinal artery occlusion patients and controls." (PMID 17438520, 2007).
retinal ischemia (1 paper, 2021). A ischemic disease that involves the retina. "As in whole blood, it has been shown that caffeine does not change the LPS-induced secretion of IL-10, IL-6, and IL-1β, while reduced mRNA expression of IL-6, IL-12, and IL-3 has been found in LPS-activated RAW264.7 cells or retinal ischemia/reperfusion-induced IL-6 and IL-1β secretion by microglia." (PMID 34371919, 2021).
rickettsioses (1 paper, 2016). "Our previous studies have clearly demonstrated that the in vivo production of IL-10 in murine models of fatal rickettsioses is associated with the severity of disease." (PMID 27362650, 2016).
rotator cuff tear (1 paper, 2022). "The serum levels of IL-10 were significantly higher among patients with rotator cuff tear with sleep disturbance compared with those of the control group (p = 0.05)." (PMID 36295022, 2022).
salpingitis (1 paper, 2025). Acute or chronic inflammation of the fallopian tube. "In this study, the effects of E2 and P4 on the expression of IL-1β, TNF-α, IL-10, and mBD-2 in LPS-stimulated fallopian tube epithelial cells, as well as the potential mediation of postinjury salpingitis through the NF-κB, MAPK, and PI3K/Akt pathways, were investigated." (PMID 40604711, 2025). "Estrogen and progesterone can protect against LPS-induced mouse salpingitis by inhibiting the activation of the NF-κB, MAPK, and PI3K/Akt signaling pathways and suppressing the expression of the inflammatory factors IL-1β, TNF-α, IL-10, and mBD-2." (PMID 40604711, 2025).
SAPHO syndrome (1 paper, 2024). SAPHO syndrome (acronym for Synovitis, Acne, Pustulosis, Hyperostosis and Osteitis) is an auto-inflammatory disease, mainly characterized by the association of neutrophilic cutaneous involvement and chronic osteomyelitis. "In SAPHO syndrome, IL-10 and TGF-β collaboratively modulate immune cell activity and inflammatory response intensity, helping to control disease activity and progression." (PMID 39286247, 2024). "In SAPHO syndrome, IL-10’s regulatory function potentially alleviates chronic inflammation and autoimmune responses by reducing the production of pro-inflammatory cytokines such as tumor necrosis factor α (TNF-α) and interleukin-1β (IL-1β)." (PMID 39286247, 2024). "This article reviews the cytokines involved in the pathogenesis of SAPHO syndrome, such as tumor necrosis factor α (TNF-α), interleukin 1β (IL-1β), IL-6, IL-10, and transforming growth factor-β (TGF-β), and discusses their potential as intervention points for treatment." (PMID 39286247, 2024).